ALDH1A1 (aldehyde dehydrogenase 1 family member A1)
Diseases named in the same sentence as ALDH1A1 in open-access papers (continued):
Sharing a sentence is not in itself a finding about the gene and the disease.
pancreatic cancer (continued). "The RT-PCR results demonstrated that the mRNA of ALDH1A1 and ALDH3A1 were significantly decreased in NRF2-siRNA transfected pancreatic cancer cells compared to those in control-siRNA transfected cells." (PMID 28671577, 2017). "Our discovery of ALDH1A1 as an AURKA substrate provides a novel mechanism by which AURKA promotes chemoresistance and stem cell formation in pancreatic cancer via ALDH1A1 and vice versa." (PMID 28193222, 2017). "To evaluate the important role of NRF2 in regulation of the expression of ALDH1A1 and ALDH3A1 in pancreatic cancer cells, we first knocked down the expression of NRF2 in pancreatic cancer AsPC-1, COLO-357 and PANC-1 cells using siRNA." (PMID 28671577, 2017). "Aldehyde dehydrogenase 1 family, member A1 (ALDH1A1) and aldehyde dehydrogenase 3 family, member A1 (ALDH3A1) have been identified as a biomarker for cancer stem-like cells including pancreatic cancer stem-like cells." (PMID 28671577, 2017). "Related to this study, our recent study has demonstrated that dasatinib enhances gemcitabine-induced decreased ALDH1A1 expression and increased cell death of MIA PaCa-2 pancreatic cancer cells with acquired resistance to gemcitabine." (PMID 28671577, 2017). "Concurrently, it was also reported that ALDH1A1+CD44+CD24+ cells correlated with metastatic activity in matched primary and metastatic samples from pancreatic cancer." (PMID 26445849, 2016). "As far as we know, this is the first data showing that a combination of ALDH1A1-siRNA and GEM has synergistic anti-tumor effects in human pancreatic cancer cells." (PMID 22710732, 2012). "This potentially powerful combination treatment of ALDH1A1-siRNA and GEM warrants further investigation as an effective therapeutic regimen to overcome the resistance of pancreatic cancer to GEM." (PMID 22710732, 2012). "Three novel proteins, ALDH1A1, STIP1 and VIM were chosen to validate and further investigate their involvement in pancreatic cancer invasion." (PMID 19216797, 2009). "IL-17 could also regulate cluster cell development and stem cell characteristics of pancreatic cancer cells by increasing the expression of DCLK1, POU2F3, ALDH1A1, and IL17RC." (PMID 39906741, 2024). "Hence, IL-17 regulates the development of stem cell features of pancreatic cancer cells by increasing the expression of DCLK1, ALDH1A1, and other stem cell markers." (PMID 39839479, 2024). "In addition, gene expression profiling of 3 pancreatic cancer cell lines indicated that AsPC-1 and BxPC3 cells primarily expressed ALDH1A3, whereas the expression of ALDH1A1 and ALDH1A3 in MIA PaCa cells was equivalent." (PMID 36651035, 2023). "Moreover, gene expression analysis of the pancreatic cancer cell lines AsPC-1, BxPC3, and MiaPaCa-2 showed that AsPC-1 and BxPC3 cells mainly express ALDH1A3, while MiaPaCa-2 cells express ALDH1A1 and ALDH1A3 in equal levels." (PMID 37686694, 2023). "In pancreatic cancer, ARID1A deletion promotes pancreatic tumorigenesis by increasing chromatin accessibility to the enhancer region of aldehyde dehydrogenase 1 family member A1 (ALDH1A1), upregulating ALDH1A1 expression, and attenuating KRAS-induced senescence." (PMID 35965507, 2022). "As AURKA overexpression is also associated with enhanced chemoresistance, we hypothesized that AURKA may upregulate ALDH1A1 leading to EMT, CSC phenotypes, and chemoresistance in pancreatic cancer." (PMID 28193222, 2017). "Phospho-resistant ALDH1A1 fully reverses EMT and CSC phenotypes, thus serving as dominant negative, which underscores the clinical significance of the AURKA-ALDH1A1 signaling axis in pancreatic cancer." (PMID 28193222, 2017). "Real-time-quantitative-PCR (qRT-PCR) and Western blotting were used to evaluate the expression profile of ALDH1A1 in seven pancreatic cancer cell lines and one non-malignant pancreatic cell line." (PMID 21708005, 2011).
pancreatic cancer (continued). "In non-malignant pancreatic tissue, adjacent to pancreatic cancer in 60 cases, we observed strong cytoplasmic expression of ALDH1A1 in the pancreatic islet cells, in the acinar epithelium and in the ductal epithelial cells." (PMID 21708005, 2011). "In pancreatic tumors, it has recently been shown that immune cell-derived IL-17 regulates the development of TCs via increased expression of DCLK1, POU domain class 2 transcription factor 3 (POU2F3), aldehyde dehydrogenase 1 family member A1 (ALDH1A1), and IL17RC." (PMID 33348546, 2020). "In pancreatic cancer, investigation of cancer stem cell lineages enabled the identification of cell membrane markers such as CD44, CD24, epithelial specific antigen (ESA) and CD133 and the expression pattern of ALDH1A1 as an important biomarker of pancreatic cancer stem cells." (PMID 28671577, 2017). "However, ALDH1A1 levels have not been analyzed in pancreatic cancer." (PMID 28193222, 2017).
colon carcinoma (64 papers, 2010 to 2025). "Thus, colon cancer stem cells secrete high levels of ALDH1A1 that cause extracellular detoxification of maphosphamide and ALDH1A1 also confers resistance of COLO 205 cells to cyclophosphamide." (PMID 25788273, 2015). "Furthermore, nuclear staining of ALDH1A1 in colon cancer was associated with a dismal prognosis." (PMID 26783961, 2016). "Statistical analysis revealed that in non-small cell lung cancer (NSCLC) and colon cancer, ALDH1A1 and ZBTB7B were positively correlated with CD274 mRNA expression." (PMID 39107297, 2024). "An in vivo study on trans-retinoic acid and colon cancer found decreased ALDH1A1 and ALDH1A3 protein expression, while ALDH1A2 protein expression remained unchanged in colon cancer progression with alterations in the gut microbiome." (PMID 37711628, 2023). "Kaplan–Meier analysis showed that high levels of both Csn6 and Aldh1a1 correlated with poor relapse-free survival in the colon cancer GSE39582 data set." (PMID 32225170, 2020). "In fact, the tumor sphere formation ability was decreased, and the levels of a panel of established CSC markers, including CD133, CD44, Sox2, Oct4, Nanog, and ALDH1A1, were decreased in colon cancer cells treated with GM‐Exo subjected to S100A9 knockdown." (PMID 31559140, 2019). "The ALDH1A1 isozyme has historically been the best studied ALDH family member linked to SCs and the ALDH1A1 isozyme specifically has also been linked to colon cancer stem cells (SCs)." (PMID 30308036, 2018). "A previous study showed that the elevated expression level of ALDH1A1 was correlated with poor prognosis in colon cancer patients." (PMID 31516883, 2018). "This is particularly encouraging because immunohistochemical analysis of ALDH1A1 expression in colon cancer is useful for the detection of nuclear expression in a small subpopulation of patients and is associated with shorter survival." (PMID 26783961, 2016). "A number of recent studies propose an important role of ALDH1A1 in the response to chemotherapy of patients with colon cancer or other neoplasias." (PMID 25788273, 2015). "RELN and ALDH1A1 are expressed in prostate cancer, ENG, SI, FCGBP and PTPRT are associated with colonic tumors." (PMID 21533145, 2011). "When tracking the colon stem‐cell populations, ALDH1A1‐positive cells are a small subpopulation of cells (≤5%) localized at the bottom of normal crypts where stem cells reside but increase during the stepwise progression to colon cancer." (PMID 36694633, 2023). "Furthermore, Csn6 expression also showed a significant positive correlation with Aldh1a1 expression in two sets of colon cancer data, the TCGA database and GSE17538." (PMID 32225170, 2020). "Suppressing ALDH1A1 through specific siRNA sensitizes colon cancer cells to chemotherapy." (PMID 30733805, 2019). "Thus, ALDH1A1 and REPS2 (mutated in 14/700, (2%) of colon tumors, and in 4/700, (0.57%) of colon tumors, respectively; Cosmic database) seem to be major mediators of nuclear DKK-1 effects." (PMID 25788273, 2015). "Comparing the secretome of colon CSCs with that of more differentiated colon cancer cells in the bulk tumor they found that CSCs secreted much higher levels of aldehyde dehydrogenase family 1, member A1 (ALDH1A1) and bleomycin hydrolase (BLMH), two enzymes able to detoxify chemotherapeutics." (PMID 24728412, 2014). "Additionally, neither cytoplasmic nor stromal expression of ALDH1A1 was associated with prognosis in colon or rectal cancer, but a small proportion of colon cancer samples were discovered to be positive for nuclear staining of ALDH1A1." (PMID 26783961, 2016). "The ALDH expression pattern of colon cancer-derived cell lines is as follows; LS-180 cells express ALDH1A1 and ALDH2 isoforms, HT-29 cells mostly express ALDH1A1 isoforms, and HCT-116 cells primarily express ALDH1A3 isoforms." (PMID 37686694, 2023).
colon carcinoma (continued). "The mRNA expression levels of the colon cancer-specific stemness markers DCLK1, LGR5, and ALDH1A1 were elevated in HT-29 as well as in Caco-2 cell-derived colonospheres and were downregulated after LTC4 stimulation." (PMID 32814764, 2020). "To examine and confirm the relationship among CSN6, TRIM21 and ALDH1A1 in human cancers, we performed IHC staining on a TMA from our human colon cancer cohort to assess the expression of CSN6, TRIM21 and ALDH1A1." (PMID 32225170, 2020). "High aldehyde dehydrogenase-ALDH1A1 activity (henceforth ALDH) was shown to identify hematopoietic, breast and colon cancer stem cells." (PMID 22276135, 2012). "Notably, we observed that PXR controls the expression of genes that were previously reported to confer CSC chemoresistance or to have a negative impact on disease-free survival in colon cancer patients, including ABCG2, ABCC6, ALDH1A1, CYP3A4, or S100A10." (PMID 27448961, 2016).
melanoma (64 papers, 2013 to 2025). A malignant, usually aggressive tumor composed of atypical, neoplastic melanocytes. "Since ALDH1A1 has been implicated in tumour-initiating capacity in melanoma and has been associated with drug resistance, we propose ALDH1A1 as a potential prognostic marker in melanoma patients." (PMID 33082334, 2020). "Of note, similar to ALDH3A1, in human melanoma ALDH1A1 was shown to associate with cancer stem-like features and therapy resistance." (PMID 31817719, 2019). "In an AhR deficient background, increased Aldh1a1 activity likely supports primary tumorigenesis and lung metastasis of melanoma cells, whereas a reduction in Aldh1a1 activity impaired the pro-tumorigenic effects caused by AhR depletion." (PMID 26242870, 2015). "Aldh1a1 appears to have a causal role in maintaining the undifferentiated status of breast, lung and prostate tumors and of soft tissue sarcomas, carcinomas and melanoma." (PMID 26242870, 2015). "Aldh1a1 overactivation in an AhR-deficient background enhances melanoma progression." (PMID 26242870, 2015). "For instance, CD44 and ALDH1A1 expressions are significantly higher in melanoma than in other skin cancers, suggesting a unique role in melanoma aggressiveness." (PMID 40867277, 2025). "Overexpression of ALDH1A1 in melanoma cells stimulates the secretion of proangiogenic factors, including IL-8, activating the DLL4-dependent Notch signaling pathway in ECs and promoting angiogenesis." (PMID 40399946, 2025). "The study found melanoma cells overexpressing ALDH1A1 exhibit resistance to vemurafenib and trametinib." (PMID 39582535, 2024). "Notch1 was also recently shown to mediate the proangiogenic activity of ALDH1A1-overexpressing melanoma cells." (PMID 39199632, 2024). "In silico TCGA analysis further revealed that melanoma tumors are enriched in ALDH1A1 and ALDH1A3 isoenzymes." (PMID 38201651, 2024). "Another recent study investigated the role of ALDH1A1, a marker indicating stem cell-like properties, in the drug resistance of melanoma cells to BRAFi/MEKi." (PMID 39582535, 2024). "ALDH1 has been found to be overexpressed in melanoma, with ALDH1A1 and ALDH1A3 being the two predominantly expressed isoforms." (PMID 39796106, 2024). "In melanoma, increased ALDH1A1 expression and activity upregulates the release of pro-angiogenic factors, and these factors modulate the angiogenic profile of ECs by rearranging the Notch pathway." (PMID 39611156, 2024). "ALDH1A1 is predominantly expressed in human melanoma tumor samples, whereas ALDH1A3 is predominantly expressed in human melanoma cell lines." (PMID 36694633, 2023). "In melanoma cells, the knockdown of AhR’s expression resulted in increased expression of the stem cell marker ALDH1a1, and the increased ALDH1a1 was found to drive enhanced invasion, migration, and tumorigenecity." (PMID 37106727, 2023). "Previously documented markers including FOXP3 (Tregs), CD163 (TAMs), CD33 (TANs), FAP (CAFs), MIA (melanoma), and ALDH1A1 (HNSC), were used for cell-type annotation." (PMID 35812726, 2022). "Strikingly, high ALDH1A1 protein expression in the IF appeared to confer worse prognosis and shorter disease-free survival in our cohort of melanoma patients." (PMID 33082334, 2020). "It has also been reported that depletion of ALDH1A1 by shRNA in melanoma cells resulted in significant delay in appearance of xenografted melanoma and reduction in tumor growth, as well as a decrease of metastases number after tail vein injection in mice." (PMID 35582039, 2020). "Here we show the induction of the self-renewal and pluripotency markers Nanog, KLF4, OCT4, and SOX2 and the over-expression of the CSC markers CD133, CD243, and ALDH1A1 in melanoma cells exposed to chronic acidosis compared with control cells." (PMID 32803272, 2020).
melanoma (continued). "Melanoma treatment with a novel irreversible isoform-specific ALDH1 inhibitor (DIMATE) or depletion of ALDH1A1 and/or ALDH1A3 results in the accumulation of toxic aldehydes, increased apoptosis, and decreased tumor growth in xenograft mouse models." (PMID 30733805, 2019). "Genetic ablation of ALDH1A1 by its specific shRNA resulted not only significant reduction in tumor growth but also exhibited significant decrease in metastatic burden in melanoma." (PMID 28137308, 2017). "A report examining melanoma CSCs described a number of genes that appear to be regulated by ALDH1A1 and/or ALDH1A3, including CDC42, a gene containing RAREs." (PMID 28423611, 2017). "Heterogeneous staining for KRT, CD206, CD204, and ALDH1A1 was observed within the pancreatic foci, as was the case with the well-differentiated islands observed with melanoma cells after subcutaneous transplantation into nude mice." (PMID 28957348, 2017). "Indeed, ALDH1A1 has been associated with the tumor-initiating cell phenotype in human melanoma, and its levels and activity could potentially be used to identify stem-like cells in melanoma tumors." (PMID 27764776, 2016). "Aldh1a1 has been associated to the cancer stem/tumor initiating cell phenotype in human sarcomas, nasopharylgeal carcinomas, breast carcinomas and melanoma, and its level of expression and/or activity could represent a potential tool to identify stem-like cells in melanoma tumors." (PMID 26242870, 2015). "AhR knockdown in mouse melanoma B16F10 cells significantly increased Aldh1a1 mRNA and protein expression as compared to wild type B16F10 cells." (PMID 26242870, 2015). "To further analyze the effects of Aldh1a1 in the metastatic burden of melanoma cells, we used retroviral transduction to produce sh-AhR-Luc and sh-AhR + sh-Aldh1a1-Luc cells expressing the in vivo marker luciferase." (PMID 26242870, 2015). "?A3B2 tlsb=-.15pt?>The inverse correlation between AhR and Aldh1a1 in mouse melanoma cells was also observed in human melanoma cells previously reported to express high (A375) or low (C8161) receptor levels." (PMID 26242870, 2015). "The effects of Aldh1a1 in maintaining melanoma progression through the control of cancer stem cells have been almost exclusively studied using xenografts of human cell lines in immunodeficient mice." (PMID 26242870, 2015). "In summary, we present evidences for the existence of a regulatory mechanism by which AhR modulates Aldh1a1 expression and activity in melanoma cells." (PMID 26242870, 2015). "We have attempted to determine Aldh1a1 levels by immunohistochemistry in our tissue microarrays (TMA) containing human melanomas expressing different amounts of AHR." (PMID 26242870, 2015). "In this study, we have found that Aldh1a1 upregulation is likely an intermediate factor promoting melanoma growth and metastasis in AhR depleted cells." (PMID 26242870, 2015). "High Aldh1a1 expression is being considered not only a marker but also a potential tool to isolate stem-like cells in melanoma." (PMID 26242870, 2015). "On the other hand, aldehyde dehydrogenase 1a1 (Aldh1a1) has been recently identified as a potential melanoma promoter and a regulator of the cancer stem cell phenotype." (PMID 26242870, 2015). "Aldh1a1 downmodulation reduced melanoma cell migration and invasion in vitro and tumor growth and metastatic dissemination in vivo." (PMID 26242870, 2015). "Aldh1a1 and AhR converge at the control of the cancer stem-like phenotype in melanoma cells, although with an opposite pattern that resembles that found for tumor growth." (PMID 26242870, 2015). "The results presented here, propose the existence of regulatory pathway between AhR and Aldh1a1 in melanoma considering that the pro-tumorigenic effects of Aldh1a1 overexpression were significantly augmented in an AhR deficient background." (PMID 26242870, 2015).